FAS (Fas cell surface death receptor)
Diseases named in the same sentence as FAS in open-access papers (continued):
Sharing a sentence is not in itself a finding about the gene and the disease.
Splenomegaly (4 papers, 2012 to 2022). Abnormal increased size of the spleen. "A definitive diagnosis of ALPS-FAS was formulated based on the 2010 revised diagnostic criteria as both required criteria were satisfied (chronic lymphadenopathy, splenomegaly, and increased TCRαβ+ DNT cells), in addition to one primary criterion (pathogenic germline mutation in FAS death domain)." (PMID 31191551, 2019).
acne (3 papers, 2023 to 2024). An inflammatory process of the sebaceous glands which is characterized by comedones, nodules, papules and/or pustules on the skin. "This review highly recommended further association studies for the candidate genes including IL6, FAS, and IFNG to identify the genetic variants playing unknown roles in the pathogenicity of acne vulgaris and receiving medications." (PMID 37228537, 2023). "Moreover, the function of the other genes, including FAS, SDC1, ANGPTL2, IL-15RA, INHBA, and OSMR in lymphocytes, keratinocytes, fibroblasts, and smooth muscle, are yet to be explored, suggesting that acne involves not only the skin’s surface but also a wider systemic dysregulation." (PMID 38854033, 2024).
alopecia areata (3 papers, 2021 to 2022). Loss of scalp and body hair involving microscopically inflammatory patchy areas. "It was reported that FAS-deficient mice avoided hair loss when induced alopecia areata." (PMID 36316632, 2022). "Anaerococcus, Neisseria and Acinetobacter which are increased in alopecia areata patients correlated negatively with the FAS and SOD2 genes but positively with the NOD2 gene." (PMID 36292745, 2022). "Association between genes PTPN22, FAS/FASL and CTLA4 with alopecia areata." (PMID 34735462, 2021).
cervical tumour (3 papers, 2015 to 2024).
cholangiocarcinoma (3 papers, 2017 to 2022). A carcinoma that arises from the intrahepatic biliary tree (intrahepatic cholangiocarcinoma) or from the junction, or adjacent to the junction, of the right and left hepatic ducts (hilar cholangiocarcinoma). "Regarding cholangiocarcinoma, HRAS, KIT and FAS have previously been associated with cholangiocarcinoma in the literature." (PMID 28178311, 2017). "Examining cholangiocarcinoma, we observed that the HRAS, KIT, ZBTB16, FAS and NCOA4 genes were altered by high methylation (shown in light sea green)." (PMID 28178311, 2017).
chordoma (3 papers, 2014 to 2022). Chordomas are rare malignant tumors arising from embryonic remnants of the notochord in axial skeleton. "The dysregulation of one or more of those mechanisms during development and later in chordoma might be the cause of FAS/FASL altered expression." (PMID 25071022, 2014). "Neverteless, the evidence here provided indicates the early role of FAS/FASL pathway during embryogenesis as a possible cause of chordoma formation, and suggests the need for persistent dysregulation of FAS/FASL pathway in later stages as a determinant for tumor onset." (PMID 25071022, 2014). "FAS/FASL expression was found to be dysregulated in chordoma leading to inactivation of the downstream Caspases in the samples analyzed." (PMID 25071022, 2014). "We were able to revert this status in U-CH1 cells by exposition to synthetic soluble Fasl, activating Caspase 8 in a time and dose dependent manner, showing that, in vitro chordoma cell line, the FAS/FASL pathway can be modulated." (PMID 25071022, 2014). "The obtained results indicate that FAS/FASL expression is dysregulated in chordoma and that the downstream Caspase 8 and 3 are mostly inactive in the SBCs analyzed." (PMID 25071022, 2014). "In turn, a dysregulation of FAS alternative splicing is caused also by the enhanced expression of the anti-apoptotic FAS isoform in chordoma." (PMID 25071022, 2014). "This study was conducted to investigate the expression of FAS/FASL pathway in a cohort of skull base chordomas and to analyze the role of fas/fasl homologs in zebrafish notochord formation." (PMID 25071022, 2014). "The obtained evidence strongly supports the implication of FAS/FASL in chordoma tumorigenesis." (PMID 25071022, 2014). "The expression studies performed in our cohort of SBCs suggest a possible involvement of FAS and FASL in chordoma onset." (PMID 25071022, 2014). "Although there was no direct evidence of the contribution of FAS/FASL dysregulation to chordoma formation, the knockdown of this pair of genes in zebrafish strikingly impaired notochord formation in the zebrafish model, suggesting their possible involvement in chordoma occurrence." (PMID 36465398, 2022). "However, we do not observe an increased expression of FAS after knockdown of KRT8 alone or followed by treatment of Doxo or Irino as determined by qRT-PCR, and this may due to the low expression of FAS in chordoma cells (data not shown)." (PMID 31767864, 2019).
dementia (3 papers, 2020 to 2022). Loss of intellectual abilities interfering with an individual's social and occupational functions. "Furthermore, expression of FAS mRNA in the para-hippocampal gyrus region, which is linked to dementia, tended to increase more in AD patients with severe cognitive impairment compared to those with moderate cognitive impairment." (PMID 33741983, 2021).
diffuse large B-cell lymphoma (3 papers, 2018 to 2024). "Diffuse large B‐cell lymphoma patients with high tumoral FAS expression had durable clinical responses and prolonged survival after CD19 CAR T-cell therapy." (PMID 38819641, 2024).
esophageal cancer (3 papers, 2016 to 2023). A primary or metastatic malignant neoplasm involving the esophagus. "In contrast, the high expression of TLR3 in KIRC, ACC, MESO, esophageal carcinoma (ESCA), and uterine carcinosarcoma (UCS); FASLG in HNSC, BLCA, and STAD; RIPK3 in COAD; RIPK1 in MESO and KIRP; FAS in ACC; and FADD in THCA was associated with good survival." (PMID 35748782, 2022). "In the previous study, we reported that FAS/FASL, as another apoptosis associated protein, was associated with the risk of esophageal cancer." (PMID 27723786, 2016).
follicular lymphoma (3 papers, 2009 to 2025). Follicular lymphoma is a form of non-Hodgkin lymphoma characterized by a proliferation of B cells whose nodular structure of follicular architecture is preserved. "Other notable subtype-specific associations include FAS and follicular lymphoma (minP = 0.006) and TNFSF13B and CLL/SLL (minP = 0.001)." (PMID 19390683, 2009).
kidney cancer (3 papers, 2010 to 2020). Primary or metastatic malignant neoplasm involving the kidney. "The 26 down-regulated microRNA had 170 direct up-regulated mRNA targets, including oncogenes VEGFA, LOX, LOXL2 and FAS, well known to be involved in kidney cancer." (PMID 20420713, 2010).
metastatic tumor (3 papers, 2022 to 2023). "The downregulation of a death receptor FAS in metastatic tumors is another way to turn off NK cells for killing the metastatic cells through the FAS/FASL pathway." (PMID 37190251, 2023). "By identifying a mechanism through which FAS expression is modified, it may be possible to use an alternative form of therapy to treat or prevent metastatic disease by inducing a higher level of FAS expression in tumor cells." (PMID 37569529, 2023).
multiple sclerosis (3 papers, 2018 to 2020). A progressive autoimmune disorder affecting the central nervous system resulting in demyelination. "To identify the major source of FAS in and around MS lesions, we performed immunohistochemistry for FAS on mixed active/inactive multiple sclerosis lesions." (PMID 31228212, 2020).
neutropenia (3 papers, 2019 to 2024). A decrease in the number of neutrophils found in the blood. "Although the exact mechanism of neutropenia induced by anti-CD20 remains unknown, several theories such as immunomediated mechanisms, silent infection, or neutrophil apoptosis triggered by the FAS/FAS ligand pathway have been proposed." (PMID 39835156, 2024).
pancreatic adenocarcinoma (3 papers, 2003 to 2020). "In the pancreatic adenocarcinoma A818-6 cell line, anti-FAS antibodies induce apoptosis in cells grown in 2D- or 3D-polarized cell cultures, independently of PTPN13 and FAS colocalization." (PMID 33322542, 2020).
pancreatic ductal adenocarcinoma (3 papers, 2015 to 2020). An infiltrating adenocarcinoma that arises from the epithelial cells of the pancreas. "Previous studies have indicated that the FAS transcriptional expression was higher in metastases than it in the primary lesion of pancreatic ductal adenocarcinoma." (PMID 31942177, 2020).
preeclampsia (3 papers, 2017 to 2025). Preeclampsia is a hypertensive disorder of pregnancy that is characterized by new-onset hypertension with proteinuria presenting after 20 weeks of gestation, and depending on mild or severe forms may initially present with severe headache, visual disturbances, and hyperreflexia. "We also described the polymorphisms of FAS-670A/G and FASL IVS2nt124A/G genes in the lymphocytes of pregnant women with preeclampsia." (PMID 32116801, 2020).
sarcoma (3 papers, 2008 to 2020). A usually aggressive malignant neoplasm of the soft tissue or bone. "CD44 is a proapoptotic factor in FAS mediated apoptosis in sarcoma cells, but is also connected to cancer drug resistance.CD44 has successfully been used as a target for liposomal encapsuled doxorubicin." (PMID 18959781, 2008).
schizophrenia (3 papers, 2012 to 2026). A major psychotic disorder characterized by abnormalities in the perception or expression of reality. "FAS+ cells were found in 2/9 controls (22.2%), 7/18 schizophrenia cases (38.9%), and 4/18 bipolar disorder cases (22.2%), with no significant change according to diagnosis (χ22 = 1.46, p = .482)." (PMID 41567988, 2026). "The increased expression of FAS and TNFR1 in astrocytes, along with increased GFAP mRNA expression and positive correlations between TNFRs and GFAP mRNAs in high-inflammation schizophrenia, suggests that reactive astrocytes could be the main source of FAS/TNFR1 in the inflamed midbrain." (PMID 41567988, 2026). "By RNA-seq, the TNF superfamily (TNFSF) pathway messenger RNAs (mRNAs) were among the most changed in high-inflammation schizophrenia (all ps ≤ .01), with TNFSF receptors (TNFR1, TNFR2, and FAS) being most highly expressed in astrocytes and microglia." (PMID 41567988, 2026). "Lastly, FAS, DR4, and TNFR2 mRNAs were increased in high-inflammation schizophrenia compared with low-inflammation bipolar/schizophrenia groups (↑29%, all p adj." (PMID 41567988, 2026). "Using RT-PCR, we confirmed that 5 TNFSF receptor mRNAs (TNFR1, TNFR2, DR4, FAS, and TWEAKR, all ps ≤ .01) were increased in high-inflammation schizophrenia/bipolar disorder cases compared with low-inflammation controls." (PMID 41567988, 2026). "We discovered that midbrain astrocytes and microglia/macrophages expressed TNFSF receptors FAS, TNFR1, and TNFR2 at low levels in controls and at high levels in schizophrenia cases." (PMID 41567988, 2026). "Since FAS and TNFR1 mRNAs were highly expressed in astrocytes in schizophrenia by snRNA-seq, we measured a marker of reactive astrocytes, GFAP mRNA, to determine whether these changes could be part of a generalized astrocyte response to inflammation." (PMID 41567988, 2026). "However, reports have shown shared cell death–related transcriptional expression between schizophrenia and bipolar disorder, including increased levels of TNFR1, TWEAKR, and FAS in serum, the frontal cortex, and the hippocampus." (PMID 41567988, 2026). "Notably, FAS and TNFR1 appeared to be more highly expressed in astrocytes in high-inflammation schizophrenia compared with the low-inflammation subgroups (blue arrows)." (PMID 41567988, 2026).
silicosis (3 papers, 2012 to 2025). Silicosis is a respiratory disease caused by breathing in (inhaling) silica dust. "AM apoptosis also contributes to the pathogenesis of TB and silicosis, with increased expression of cellular apoptosis receptors (FAS) and their ligands (FASLG and TNFα), promoting the recruitment of inflammatory cells." (PMID 40531729, 2025).
Stroke (3 papers, 2023 to 2025). Sudden impairment of blood flow to a part of the brain due to occlusion or rupture of an artery to the brain. "FAS inhibition worsens stroke injury by promoting BBB breakdown and inflammation." (PMID 40880849, 2025).
vitiligo (3 papers, 2020 to 2025). Generalized well circumscribed patches of leukoderma that are generally distributed over symmetric body locations and is due to autoimmune destruction of melanocytes. "Interestingly, it has been reported that polymorphisms in the Fas promoter regions FAS-1377 AA and FAS-1377 AG have been correlated with increased risk of vitiligo, although such polymorphisms have been associated with diminished promoter activity." (PMID 41007740, 2025). "The FAS polymorphisms (FAS‐1377A>G) and FASLG SNP rs78037977 are reported to be associated with higher vitiligo risk." (PMID 33200838, 2021). "FAS and FASLG polymorphisms are also critical members of vitiligo SNPs." (PMID 33200838, 2021).
amyloidosis (2 papers, 2013 to 2025). A disorder characterized by the localized or diffuse accumulation of amyloid protein in various anatomic sites. "The same group claimed that sFAS can behave like a FAS antagonist and inhibit FAS-promoted apoptosis and amyloidosis." (PMID 39934489, 2025).
Arthritis (2 papers, 2020 to 2021). Inflammation of a joint. "Thus, FAS may have the potential to treat inflammatory disorders, such as arthritis." (PMID 32774425, 2020).
autoimmune lymphoproliferative syndrome type IA (2 papers, 2022 to 2025). "Additionally, the heterozygous germline mutation involving the FAS gene TNFRSF6 is identified in some RDD patients with an autoimmune lymphoproliferative syndrome type Ia." (PMID 36358690, 2022).
Azoospermia (2 papers, 2019 to 2025). Absence of any measurable level of sperm,whereby spermatozoa cannot be observed even after centrifugation of the semen pellet. "The prevalence rate of FAS-670A/G gene polymorphism was statistically significant among both azoospermia and oligospermia subgroups, the homozygous mutant genotype GG (p=0.014 and p=0.043), and mutant allele G (p=0.001 and p=0.004), respectively." (PMID 40531769, 2025).
Bladder tumor (2 papers, 2024). "Among the molecules involved in FAS signaling, the death receptor FAS, i.e., its deficiency, has been shown to be the most important in the progression of bladder tumors, which is in accordance with our finding that high FAS predicts superior outcome and longer overall survival in UBC." (PMID 38791085, 2024). "For instance, the UBC® Rapid test and UBC ELISA kit, the XPERT BC Monitor, BC UroMark, TaqMan® Arrays, Soluble FAS (sFAS), Bladder tumor fibronectin (BTF), and IGF2 and MAGE-A3 are among the newest biomarkers under investigation." (PMID 39678505, 2024).
carcinoma in situ (2 papers, 2017 to 2024). "High FAS expression was more frequently found in invasive UBC associated with carcinoma in situ (p = 0.038), as well as in tumors with lymphocyte-rich stroma (p = 0.033)." (PMID 38791085, 2024). "High DR4 expression is more frequently found in low-grade tumors, as well as in UBC associated with exposition to known carcinogens, while high FAS indicates carcinoma in situ adjacent to the invasive tumor." (PMID 38791085, 2024).
chondrosarcoma (2 papers, 2016 to 2021). A malignant cartilaginous matrix-producing mesenchymal neoplasm arising from the bone and soft tissue. "In chondrosarcoma cells, curcumin, which is a bioactive component isolated from Curcuma longa, upregulated FAS and FASL and increased CASPASE 3 and 8 activities." (PMID 34083947, 2021).
chronic hepatitis (2 papers, 2010 to 2016). An active inflammatory process affecting the liver for more than six months. "Down-regulation of FAS/FAS-L has been detected in patients with chronic hepatitis caused by HCV, suggesting a role of FAS-mediated hepatocytic apoptosis in eliminating infected cells." (PMID 20334631, 2010).
Cognitive impairment (2 papers, 2021 to 2025). Abnormal cognition is characterized by deficits in thinking, reasoning, or remembering. "For FAS, we found an area‐under‐curve (AUC) of 0.759 (95% CI, 0.618–0.899), with 28.75 as the optimal cut‐off score for predicting subsequent cognitive impairment (sensitivity: 0.776, specificity: 0.333) according to Youden index." (PMID 39891470, 2025).
developmental delay (2 papers, 2016 to 2018). "Prenatal alcohol exposed children at-risk for developmental delays, or who meet the diagnostic classification for FAS, are those whose mothers consumed alcohol frequently, for prolonged periods, at moderate-to-heavy doses, and binges." (PMID 30619064, 2018).
E. Coli infection (2 papers, 2022). "The expression of genes and proteins related to fatty acid anabolism was downregulated by E. coli infection, including SREBP1, SCD, FAS, and PPARγ." (PMID 36341408, 2022).
endometrial carcinoma (2 papers, 2017 to 2021). A malignant tumor arising from the epithelium that lines the cavity of the uterine body. "Sorafenib, a broad-spectrum kinase inhibitor targeting the RAF–MEK–ERK pathway, enhanced sensitization to TRAIL- or FAS-mediated apoptosis by downregulation of cFLIP in endometrial carcinoma cell lines that are resistant to TRAIL or FAS." (PMID 33477367, 2021). "A previous study reported that inhibition of CK-2 by TBB decreased the endogenous cFLIP levels via proteasome-mediated degradation of cFLIP, leading to the enhancement of TRAIL and FAS sensitivity in endometrial carcinoma cells." (PMID 28086218, 2017).
epilepsy (2 papers, 2016 to 2022). A brain disorder characterized by episodes of abnormally increased neuronal discharge resulting in transient episodes of sensory or motor neurological dysfunction, or psychic dysfunction. "Other targets, such as the NFkB subunits and regulators or the decoy receptor of FAS, TNFRSF6B, whose gene upregulation has never been associated with epilepsy, should be investigated." (PMID 27006531, 2016).
esophageal squamous cell carcinoma (2 papers, 2013 to 2021). Esophageal squamous cell carcinoma (ESCC) is a type of esophageal carcinoma (EC) that can affect any part of the esophagus, but is usually located in the upper or middle third. "FAS -670A > G and FASLG -844 T/C polymorphisms have been previously associated with an increased risk of HNC, gynecological cancer and esophageal squamous cell cancer, whereas FAS -670A > G has been also associated with an increased risk of recurrence and death in epithelial ovarian cancer patients." (PMID 34078296, 2021).
falciparum malaria (2 papers, 2011 to 2013). "Other important components of THαβ immune response included up-regulation of HMOX1, FAS, BCL6, TNFRSF10A, and MIP1α were noted in Griffiths’ research, which studied the peripheral blood leukocytes from Kenyan children with acute falciparum malaria." (PMID 24188121, 2013).
Hashimoto thyroiditis (2 papers, 2013 to 2020). An autoimmune disorder caused by the production of autoantibodies against thyroid tissue. "In case of Hashimoto's thyroiditis, a TH1 disease, the cytokine interferon-gamma appears to play a crucial role in the pathology of the disease by enhancing the expression of caspases and thereby sensitizing cells to FAS-mediated apoptosis." (PMID 23878745, 2013).